LINC01448 (long independently transcribed non-coding RNA 1448)
Gene: Long non-coding RNA gene on chromosome 7 (42,661,716 to 42,706,447, reverse strand). Ensembl gene ENSG00000238284.
Diseases named in the same sentence as LINC01448 in open-access papers:
LINC01448 is named in the same sentence as 1 disease in open-access papers, as found by Europe PMC text mining. Sharing a sentence is not in itself a finding about the gene and the disease.
LINC01448 shares sentences with these, for which no sentence is quoted: tumor (1 paper).